IL10 (interleukin 10)
Diseases named in the same sentence as IL10 in open-access papers (continued):
Sharing a sentence is not in itself a finding about the gene and the disease.
tumor (continued). "Second, TRMBE and 5-FU combined therapy regulated the blood cytokines (IL-6, IL-10, TGF-β, IFN-γ), immune cells in spleen (PMN-MDSCs), and modulated the tumor microenvironment, most notably the percentage of infiltrating PMN-MDSCs, NK cells, and PD-1+ CD8+ T cells." (PMID 35656301, 2022). "In particular, in PCa pSTAT-3 and IL-6R are present in 95% of metastatic niches of patients who die of castration-resistant PCa (CRPC); this suggests that in PCa, the activation of STAT-3 mediated by IL-6, IL-10 and EGF serves an important role for tumor progression and development of metastasis." (PMID 35703345, 2022). "Besides, the expression of IL-6 and TNF-α were upregulated while the expression of IL-10, CCL22, Arg-1 and CD206 were downregulated in the tumor tissues from ACEA-treated group." (PMID 35641479, 2022). "These long-lived immune cells exert their regulatory functions in immunity and inflammation by producing key inflammatory mediators, such as tryptase, VEGF, IL-10, TGF-β1, and MMP9, and the relevant data of their anti-tumor or pro-tumor features have been reported." (PMID 35874749, 2022). "Mast cells can stimulate tumor cell expansion by releasing cytokines and growth factors, including fibroblast growth factor-2 (FGF-2), nerve growth factor (NGF), platelet-derived growth factor (PDGF), IL-10, and IL-8, into the tumor stroma." (PMID 36430483, 2022). "Recent studies have demonstrated that M2-like TAM-derived factors, such as interleukin (IL)-6, IL-10, and milk fat globule-epidermal growth factor VIII (MFG-E8), can suppress naïve T cell proliferation, promote carboplatin resistance, and enhance tumor growth." (PMID 36303162, 2022). "Cytokine levels significantly correlated with tumor grade (IL-6; p = 0.0070), prevalence of distant metastasis (IL-18; p = 0.0313), and disease progression over time (IL-10; p = 0.0033) but not tumor location." (PMID 36294509, 2022). "In addition, the expression profile of the tumor-immunoregulatory genes TNF-α, TGF-β, IL-10, and iNOS was determined in macrophages conditioned with OSCCs tumoral media previously treated with PL, in comparison with non-treated cells." (PMID 36686704, 2022). "However, regulatory B (Breg) cells, as a newly designated group, appear to prevent T cell differentiation and promote tumor growth via transforming growth factor-β (TGF-β) and/or interleukin-10 (IL-10) release." (PMID 36339942, 2022). "Tumor cells and other cells in the TME may prevent NK-cell activation and inhibit their function by secreting a variety of cytokines (including IL-6, IL-10, TGF-β, PGE2, and IDO)." (PMID 36439457, 2022). "Altered-immunosuppressed tumor shows an intermediate degree of T cell and CTL infiltration and immunoscore, T cell checkpoints (PD-1, CTLA-4, TIM3, and LAG3), immune suppressive cells (MDSC and Treg), and inhibitory cytokines (TGF-, IL-10 and VEGF)." (PMID 36293435, 2022). "Interestingly, tumor-intrinsic PKD3 has been described to promote immune escape by enhancing expression of Fas and PD-L1 as well as secretion of TGF-β, CCL-21 and IL-10, all of which are critical to establish an immunosuppressive tumor microenvironment." (PMID 35440091, 2022). "Furthermore, LAG-3 marks Tregs releasing immunosuppressive cytokines, such as IL-10 and TGF-β1, with a more suppressive phenotype than LAG-3-negative cells from the tumour sites of cancer patients." (PMID 35328510, 2022). "In addition, CSCs maintain the immunosuppressive TME and enhance tumor infiltration by releasing diverse immunosuppressive cytokines and chemotactic factors such as TGF-β, IL-10 and IL-2." (PMID 36207500, 2022). "As an immunosuppressive factor, IL-10 can inhibit the expression of MHC-II to reduce antigen presentation, thus inducing immunosuppression to promote tumor escape; therefore, the reduction in IL-10 levels plays an immune activation and anti-cancer role to some extent." (PMID 36559180, 2022).
tumor (continued). "In addition, we measured the cytokines IL-1, IL-10, and TNF-α produced by the tumor-conditioned macrophage media." (PMID 36686704, 2022). "Inflammatory cytokines that suppress host anti-tumor activity include TGF-β and IL-10." (PMID 35892729, 2022). "M1 macrophages are pro-inflammatory cells that have bactericidal and tumor-killing activities, while M2 macrophages are involved in tissue remodeling and promoting fibrosis and mainly secrete anti-inflammatory factors such as TGF-β1 and IL-10." (PMID 36605402, 2022). "Thus, Treg cells inhibit the activity of migrating immune cells to the tumor environment by secreting inhibitory cytokines (TGF, IL-10) and expressing inhibitory molecules (CTLA-4)." (PMID 35954362, 2022). "However, M2 macrophage can secrete inhibitory cytokines, such as IL-10 or TGF-B, to downregulate immune response and promote the development of tumor." (PMID 36105106, 2022). "The anti-inflammatory markers (IL-10, CCL18, and TGF-β) were upregulated, and the pro-inflammatory markers (TNF-α and IL-6) were downregulated by the macrophages that are differentiated within the tumor matrices." (PMID 36072957, 2022). "TGF-β and IL-10 expression decrease synthesis of IFNγ and TNF-α by pro-inflammatory CD4 T cells, and in turn reduce tumor-specific cytotoxicity of CTLs, prevent activities of dendritic cells and NK cells, and result in tolerance to tumor cells." (PMID 35372046, 2022). "M2 type macrophages also participate in this suppression of the immune response process by secreting many cytokines, including IL-10 and TGF-β, which in addition to suppressing immune response, participate in tissue repair and matrix reconstruction, and promote tumor progression." (PMID 35865015, 2022). "Recent studies have shown that CAR-T cells combined with IL-10 monoclonal antibody (mAb) can partially alleviate bone marrow cell-mediated immunosuppression by blocking IL-10 signaling, while promoting CAR-T cells expansion and enhancing killing effect, thereby increasing anti-tumor function." (PMID 36238297, 2022). "Studies have showed that glioma-infiltrating GAMs were polarized to M2 phenotype by secreting robust quantities of immunosuppressive cytokines like IL-10 and TGF-β1 which were capable of augmenting tumor immune suppression as well as accelerated tumor progression." (PMID 35419058, 2022). "Additionally, HS1793 reduced the number of Tregs and lowered IL‐10 and TGF‐β secretion in irradiation tumour‐bearing mice." (PMID 35384373, 2022). "In contrast, the involvement of ICOS-Fc in this mechanism is unlikely, since our previous work has shown that ICOS-Fc decreases IL-10 expression in the tumor mass when loaded into cyclodextrin nanosponges, but not in PLGA nanoparticles." (PMID 36500861, 2022). "Tumor-infiltrating M1-type macrophages (anti-tumorigenesis) secrete proinflammatory cytokines (e.g., IL-1β and TNF-α), whereas tumor-infiltrating M2-type macrophages (pro-tumorigenesis) secrete anti-inflammatory cytokines (e.g., IL-6 and IL-10)." (PMID 36246355, 2022). "TGF-β, IL-10 and VEGF are representative factors of tumor environment." (PMID 35806328, 2022). "In addition, in the tumor microenvironment there are M2d macrophages, which are activated by TLR antagonists, and secrete IL-10 and vascular endothelial growth factors (VEGF), which are involved in angiogenesis and tumor progression." (PMID 36341426, 2022). "These TIMs then release a wide array of factors, such as matrix metalloproteinases, IL-10, epidermal growth factor (EGF), vascular endothelial growth factor (VEGF), and IL-17, which are involved in the stimulation of proliferation and migration of tumor cells." (PMID 35884700, 2022). "IL-10 produced by MDSCs induce increased expression of lymphocyte activation gene 3 (LAG3) and the consequent decreased IL-2, IL-12, and IFNγ secretion by T cells, which hampered their proliferation and anti-tumor activity." (PMID 35757002, 2022).
tumor (continued). "In this experiment, ABP treatment inhibited the phosphorylation of STAT3, reduced the expression of IL-6 and increased the expression of IL-10, indicating that the anti-inflammatory effect of ABP may be one of its anti-tumor effects." (PMID 35264966, 2022). "Tumor cells can release various immunosuppressive factors, such as adenylate, indoleamine 2,3-dioxygenase 1 (IDO), prostaglandin E2 (PEG2), interleukin-10 (IL-10), and transforming growth factor-β (TGF-β), to inhibit the activation of immune cells." (PMID 35223466, 2022). "In summary, we revealed that miR‐192‐5p promotes GC EMT, thereby promoting malignancy and FOXP3+ Treg cell differentiation via RB1/NF‐κBp65/IL‐10 axis, thereby highlighting the miR‐192‐5p/RB1/NF‐κBp65/IL‐10 pathway as a new therapeutic strategy for tumour immunotherapy in GC." (PMID 35969010, 2022). "Cross-talk between tumor cells and TIB may help to shift the immune response towards and immunosuppressive state through induction of IL-10 expression and release by tumor cells." (PMID 35255925, 2022). "MDSCs release IL-10 to downregulate IL-12 secretion by macrophages while macrophages in turn induce MDSCs to increase IL-10 which decreases IL-6 and TNF-α in macrophages and therefore skewing the immunity towards tumor promoting type 2 response." (PMID 35183252, 2022). "GBM tumor cells promote M2 GAM polarization by activation of STAT3, NF-κB, Wnt-3a, and mechanistic target of rapamycin (mTOR), resulting in upregulation of IL-10 levels." (PMID 35572545, 2022). "IL-10 counteracted IFN-γ effects on the PD-1/PD-L1 pathway, which induced tumor resistance to ICIs." (PMID 36140220, 2022). "Also, the concomitant overexpression of IL-10 and MMP-21 was observed in tumor samples with stage III (p = 0.027)." (PMID 36437782, 2022). "Importantly, the interaction of glioblastoma cells with human pericytes induces expression of anti-inflammatory cytokines IL-10 and TGF-β, which prevent attack of the tumor by host T cell mechanisms, hence promoting tumor survival." (PMID 35581998, 2022). "They found that dendrosomal curcumin increases the gene expression of STAT4 and IL-12 in tumor and spleen tissues, probably reflecting the high levels of M1 macrophages, and decreases the gene expression of STAT3, IL-10, and arginase-1, indicating low levels of M2 macrophages." (PMID 36142391, 2022). "The function of T cells is dependent on their interaction with tumour cells and other TME cells, thereby, the factors influencing its activation include (apart from metabolic factors) TGF-β, IL-10 and ROS (by TAMs); Arg1, iNOS and ROS (by MDSCs); PD-L1 or CD80 receptors expression (in tumour cells)." (PMID 35406451, 2022). "M2 macrophages exert anti-inflammatory effects by secreting anti-inflammatory cytokines, such as IL-4, IL-10, IL-13, and TGF-β, and producing scavenger receptors and other substances; promoting proliferation, invasion and metastasis of tumor cells by inhibiting T-cell activity." (PMID 36131942, 2022). "Similarly, B1a Bregs (CD19+CD5+CD43+) have been described to use IL-10 to inhibit IFNγ and TNFα production by CD8+T cells thus negatively regulating tumour immunity against melanoma cells." (PMID 35350071, 2022). "Also, the presence of IL-10, TGF-β, and prostaglandins in the tumor microenvironment play the role of immunosuppressors that inhibit the anti-tumor activities of NK, T and B cells [32, -34]." (PMID 35283421, 2022). "TAMs also secrete IL-6 and IL-10, which activate the STAT3 pathway and promote tumor proliferation." (PMID 36532066, 2022). "Furthermore, Treg and Breg cells produce cytokines such IL-10 and TGF-B that mitigate cellular immunity and help the tumor progress." (PMID 35632488, 2022). "In our study IL10 was higher compared to the control in tumors, tumor-adjacent and not tumor-adjacent segments in the proximal part of the colon." (PMID 36555251, 2022).
tumor (continued). "Interestingly, the PUVA therapy was accompanied by an increase in the level of IL10 and IFN-γ by 10% (p=0.021) and 4.75 times (p=0.038) in the tumor tissue, respectively." (PMID 35237320, 2022). "However, they also promote tumor progression through a variety of molecules such as CTLA4, IL2, and IL10." (PMID 35267668, 2022). "Tumor-derived cytokines such as PGE2, IL-10, IL-1, TGF-β and VEGF may induce the differentiation of immature myeloid cells (CD33+ cells) into MDSCs." (PMID 36439472, 2022). "In contrast, M2 macrophages secrete anti-inflammatory cytokines such as IL-10, IL-13, IL-4, arginase-1, mannose receptor (MR, CD206), and scavenger receptor, which tend to exert an immunosuppressive phenotype that benefits tissue repair and tumor progression." (PMID 35965509, 2022). "SCF enhances tumor growth through the production of VEGF, IL-6, IL-10, and TNFα." (PMID 36313712, 2022). "Targeting IL-10 in the TME has been shown in translational studies to enhance T cell anti-tumor responses in otherwise immune cold tumors lacking the infiltration of T cells." (PMID 36310582, 2022). "One discrepancy between the in vitro and the in vivo Secretory cDC involved IL-10: it was highly produced at the protein level in vitro and expressed by the pRNA-DC at the transcriptomic level but not by tumor cDC2 in RNAseq data." (PMID 35418195, 2022). "Furthermore, macrophages, attracted into the tumour microenvironment in response to MCP-1, produce TGFβ and IL-10 which suppress the cytotoxic activities of Th1 cells." (PMID 36038791, 2022). "Furthermore, HCMV-infected glioma stem cells (GSCs) release CMV IL-10, which interacts with monocytes to enhance CMV transcriptional activity and subverts them to a tumor-supportive M2 macrophage/microglia phenotype." (PMID 35515137, 2022). "Besides, berberine inhibits tumor antigen-mediated IL-6 and TGF-β expression as well as IL-10 proliferation but restores anti-tumor cytotoxicity of T cells in the tumor microenvironment." (PMID 36439106, 2022). "Also, IL-10 and heat shock protein 90 (HSP90) expression revealed a highly significant correlation in advanced Gleason grading and tumor, node, and metastasis (TNM) staging cases of PCa." (PMID 36338516, 2022). "Dividing the population according to their progression after 16 weeks, the elevation of IL-10 in the blood samples correlated with a higher CD4/CD8 ratio in tumor and non-tumor tissues and a poor prognosis." (PMID 36230554, 2022). "Likewise, VEGF in combination with IL10 and prostaglandin E2 (PGE2) promotes a tumor endothelial ‘death barrier’ that is established by Fas-L expression to exclude CD8+ T cells preferentially over Tregs." (PMID 36175961, 2022). "Among them IL-1, IL-6, epidermal growth factor (EGF) help tumor cells survive, VEGF and IL-8 promote angiogenesis, M2 macrophages, and MDSCs antagonize inflammatory responses, IL-10, TGF-β, C-C motif chemokine ligand (CCL17) inhibits tumor immune function, and TGF-β and MMP promote tumor metastasis." (PMID 36686745, 2022). "As IL-10 and IL-4 are known to promote class switching to IgG4, these findings indicate that TNBC may create a tumor microenvironment that supports class switching to the IgG4 subtype." (PMID 35255925, 2022). "Tumor draining lymph nodes (TdLN) and tumor-infiltrating lymphocytes (TILs) were harvested from tumor-bearing mice (or inguinal lymph nodes from control naive animals) at day 20 post-tumor injection, and the expression of CD45, CD4, Foxp3, CD49b, and IL-10 was analyzed by flow cytometry." (PMID 35860556, 2022). "Recently, macrophages were expanded to IL-10-producing cells and some non-hematopoietic cells, including epithelial and tumor cells." (PMID 35222434, 2022).
tumor (continued). "In this study, we showed that N. caninum injection increased infiltration of CD8+ T cells and macrophages into the tumor, along with increased expression of IL-12, IFN-γ, IL-10, TNF-α, and IL-2 mRNA, which can also be induced by N. caninum in a mouse model, as reported in other studies." (PMID 36138417, 2022). "Researchers found that tumor-associated macrophages (TAM) display M2 macrophage characteristics and produce anti-inflammatory cytokines such as interleukin (IL)-10, IL-13 and transforming growth factor-β (TGF-β), promoting tumor initiation, growth, progression, metastasis, and immune evasion 9-12." (PMID 35637970, 2022). "As an immunosuppressive microenvironment is favorable for tumor growth and progression, we measured the levels of proinflammatory cytokines (IFN-γ, TNF-α, GM-CSF, and IL-2) and anti-inflammatory cytokines (TGF-β, IL-17, IL-10, and IL-4) within tumors." (PMID 36429032, 2022). "M2 MΦs induce tumour progression by driving tumour proliferation directly or indirectly by dampening T-cell functions through the secretion of cytokines and factors such as TGF-β, IL-10, IL-4, vascular epidermal growth factor (VEGF) and matrix metalloproteases (MMPs)." (PMID 35454848, 2022). "Nonetheless, the expression of inhibitory and suppressive markers, including genes for IL-4R, IL-10, IL-6, VEGFA, CCL2 and IL-1β, were mostly expressed by cluster 0, suggesting that these cells had a tumor-promoting and immune-suppressing functions, which resemble MDSC-like cells." (PMID 34025646, 2021). "The results showed that IL-2, IL-12, IL-17, TNF-α, and INF-Υ, which were immunity promoting cytokines, were significantly upregulated in drug serum, while IL-10, TGF-β, VEGF, and MMP-9, which were immunity abating or tumor promoting proteins, were significantly downregulated in drug serum." (PMID 33505491, 2021). "When stimulated by Th2 cytokines, including M-CSF, GM-CSF, IL-4, IL-10, and TGF-β, macrophages differentiate into the M2 phenotype, which is equipped with the functions of immune suppression, facilitating tumour progression, cell proliferation and angiogenesis." (PMID 34930387, 2021). "In contrast, M2-like cells not only produce tumor growth factors such as IL-6 but also produce angiogenic molecules, including VEGF and immunosuppressive factors such as arginase 1 (Arg1), IL-10, TGF-β, and indoleamine 2,3-dioxygenase (IDO), resulting in tumor promotion." (PMID 34071550, 2021). "Interestingly, the overexpression of CD155, IL-10, and TGF-β demonstrated predominance in the early stages of tumor development, while PD-L1 expression peaked during the later stages." (PMID 34483843, 2021). "Furthermore, TAMs contribute to the release of immunosuppressive cytokines, such as IL-10 and TGF-β, that promote tumour growth and decrease response to CAR T cell therapy." (PMID 34831165, 2021). "MDSCs promoted EMT of tumor cells through TGFβ, VEGF, and IL-10." (PMID 34768810, 2021). "PDAC has recently been found to impair NK cell tumor cell recognition and function by the regulation of several mediators, including transforming growth factor beta (TGF-β), interleukin (IL)-10, indoleamine 2,3-dioxygenase (IDO), and matrix metalloproteinases (MMPs)." (PMID 34930261, 2021). "IL-10 exerts regulatory effects on inflammatory pathways involving STAT3 and NF-κB, which may influence tumour progression." (PMID 34944729, 2021). "While reducing the number of Tregs within the primary tumor and reducing the ability of the remaining Tregs to promote EMT, LFPRLR SMO treatment did not affect the ability of Tregs to produce the classical immune suppressive cytokines, IL-10 and TGF-β1." (PMID 34375938, 2021). "In addition, IL-10 knockout animals have been shown to be resistant to UVR-induced skin carcinogenesis, demonstrating the pro-tumor role of IL-10." (PMID 33917793, 2021). "In addition, a subset of “regulatory” B cells (Breg cells) can express inhibitory cytokines such as IL-10, TGF-β or IL-35 and favor tumor progression." (PMID 33572260, 2021).